SRGN (serglycin)
Diseases named in the same sentence as SRGN in open-access papers (continued):
Sharing a sentence is not in itself a finding about the gene and the disease.
tumor (continued). "Single-cell analysis revealed SRGN expression across 17 distinct cell subpopulations, with higher expression in macrophages in tumor tissues compared to those in normal tissues." (PMID 41476965, 2025). "We suggest targeting the SRGN pathway in immune‐competent animal models to evaluate its anti‐tumour efficacy." (PMID 41410182, 2025). "Comparative feature plots and volcano plots showed SRGN was upregulated in carcinoma cells, LVECt, and HSCs when the tumor proliferated or metastasized." (PMID 40384866, 2025). "Immunohistochemical studies reveal elevated SRGN expression in advanced tumors and activated tumor microenvironment (TME) across various cancers." (PMID 41476965, 2025). "We focus on elucidating the underlying mechanisms of SRGN in PLC, particularly its interactions with tumor-associated macrophages (TAMs) in the TME." (PMID 41476965, 2025). "Collectively, these results demonstrate that CAFs promote OSCC growth and invasion in vivo via autophagy‐mediated SRGN secretion, and that short‐term intervention targeting this pathway can generate sustained tumour‐suppressive outcomes." (PMID 41410182, 2025). "Our single-cell analyses revealed a marked upregulation of SRGN in macrophages, suggesting its role in modulating macrophage function within the tumor microenvironment." (PMID 41476965, 2025). "scRNA-seq identified SRGN as a pan-cellular marker of aggressiveness, with tumor cell subclusters, LVECt, and HSCs showing stage-dependent upregulation during metastasis, directly aligning with advanced clinical phenotypes." (PMID 40384866, 2025). "In our study, an integrative approach further reveals that highly expressed SRGN promotes aggressive phenotypes of HCC tumor cells." (PMID 40384866, 2025). "The SRGN mRNA expression was examined in THP-1 cells, M0 macrophages, M1 and M2 macrophages, as well as tumor-associated macrophages (TAMs) differentiated by HepG2SG or HepG2-NC cells." (PMID 41476965, 2025). "Initially identified as a hematopoietic proteoglycan, SRGN is now known to be expressed by various cell types including tumor cells." (PMID 40542654, 2025). "Known stem cell markers in HCC development, such as CD4466, ABCG267, BMI168, and EPCAM69, were highly expressed in SRGN-overexpressed tumor cell subgroups from various stages of differentiation." (PMID 40384866, 2025). "In total, the regulatory role of SRGN in the tumor microenvironment is highlighted due to its involvement as supporter and amplifier of inflammatory and proteolytic response, reshaping concomitantly the cellular neighborhoods." (PMID 38672477, 2024). "Further experiments showed that recombinant REG4 (rREG4) activated CREB1 and upregulated SRGN expression in tumour cells." (PMID 38862740, 2024). "REG4 activates CREB1 by interacting with its receptor, EGFR, in tumour cells, resulting in increased SRGN expression." (PMID 38862740, 2024). "Overall, SRGN is a crucial factor in the tumor microenvironment controlling inflammatory and proteolytic remodeling molecules that contribute to the aggressive nature of GBM, as well as the infiltration and activation of stromal fibroblasts." (PMID 38672477, 2024). "These included well-known receptor tyrosine kinase genes (EGFR, TEK and OSMR) that activate MAPK and PI3K signaling pathways, and other tumor-promoter genes (ATP8B2, DAAM1, SLAMF8 and SRGN) as well as tumor-suppressor genes (A2M, DAPK1, RASSF8 and SOCS3)." (PMID 37190308, 2023). "More importantly, STEAP4 and ADGRF5 specifically expressed in subgroup 3 and 4 showed a significant overexpression of CXCR4 and SRGN, which were closely related to tumor metastasis or immunosuppression in TME." (PMID 37221625, 2023). "Here, expression analysis showed that SRGN is highly expressed in dendritic cells, T-cells, myeloid cells, and mast cells in the tumor tissue, and with lowly detectable expression of SRGN in the cancer cells." (PMID 35494005, 2022).
tumor (continued). "SRGN is expressed by various cells such as hematopoietic, endothelial, smooth muscle cells, fibroblasts, and tumor cells." (PMID 36358747, 2022). "For Fra-2 cl 2 primary tumours, genes such as SRGN (Serglycin) and ESAM were upregulated, while CD99 and SELPLG (selectin P ligand) were downregulated." (PMID 34693476, 2022). "Previous reports have also highlighted the role of serglycin in regulation of the biosynthesis of inflammatory mediators and growth factors in immune cells, platelets, endothelial, and tumor cells." (PMID 35494005, 2022). "Serglycin also controls the proteolytic potential of tumor cells via regulating the expression and activity of MMPs." (PMID 35494005, 2022). "In multiple myeloma, high expression of SRGN inhibits the complement activity and helps tumor cells to escape from immune surveillance." (PMID 34556636, 2021). "In previous studies, the number of SRGN was found to be highly expressed in multiple tumors and promoted the invasion of tumor cells." (PMID 34493692, 2021). "SRGN knockdown in stromal cells inhibits tumor growth and bone destruction in a patient-derived orthotopic xenograft model of mice." (PMID 34556636, 2021). "To explore the different expression of SRGN between tumor and normal tissues, we used Oncomine database for analysis." (PMID 32370744, 2020). "In TIMER database, after adjustment of age, gender, ethnicity, tumor stages and tumor purity, we found that lower SRGN expression was only significantly correlated with poor survival of SKCM patients." (PMID 32370744, 2020). "In a subset of NSCLC cells, SRGN is overexpressed and readily secreted to the tumor microenvironment." (PMID 31898491, 2020). "In parallel, in accordance to previous reports that CD44 regulates Rho-family of GTPases to promote tumor progression, we show that SRGN promoted cytoskeleton reorganization via inducing Rac1 and CDC42 activation." (PMID 31898491, 2020). "Chondroitin sulfate-decorated serglycin has previously been observed in serum-derived EVs, and found to play an important role in tumor-derived EV protein cargo loading." (PMID 32842648, 2020). "The role of serglycin in malignancies is rather intriguing because it appears to mediate interactions between tumor cells and TME, suggesting for serglycin to be a modulator within the complex tumor “ecosystem”." (PMID 28445977, 2017). "Further, we provide evidence that MCs can have a potential role in serglycin induced tumor progression by activating a CD44-related signaling pathway." (PMID 28445977, 2017). "Here we demonstrate that serglycin plays a critical role in the protein cargo loading of tumor-derived exosomes." (PMID 29088739, 2017). "These enrichment scores suggest that the deletion of serglycin affects the ability of the tumour cells to adhere to and signal to endothelial cells, and thereby interferes with the extravasation." (PMID 27223472, 2016). "The global transcription analysis of primary tumour tissue allowed us to evaluate if the targeted deletion affects the expression of genes surrounding the serglycin gene at chromosome 10, ± 500kb." (PMID 27223472, 2016). "A high level of expression of serglycin in tumour cells has been correlated to poor prognosis and an increased metastatic potential." (PMID 27223472, 2016). "To identify serglycin-dependent mediators potentially involved in tumour progression, we next analysed the tumour tissue from SG+/- and SG-/- mice with multiplex antibody arrays." (PMID 27223472, 2016). "For example, serglycin modified with CS chains enriched with 4-sulfated disaccharides is responsible for conferring tumor cells resistance against immune system attack mediated by the activation of the classical and lectin pathways of complement." (PMID 26581653, 2015). "This knowledge is important for further understanding of functions and mechanisms of serglycin in endothelial cells in tumor biology and development of diabetic complications." (PMID 26694746, 2015).
tumor (continued). "The effect of serglycin expression on tumor growth and tumor cell proliferation has been addressed in several different in vivo and in vitro models to date." (PMID 25978773, 2015). "Our results show that the presence of serglycin suppresses spontaneous tumor growth and affects angiogenesis and vascular function in vivo." (PMID 25978773, 2015). "The mechanism by which serglycin alters tumor cell aggressiveness is still elusive, however differential expression of serglycin seems to affect the expression levels of markers of epithelial to mesenchymal transition both in vitro and in vivo." (PMID 25978773, 2015). "Numerous studies have shown that serglycin is constitutively secreted by tumor cells and in some cases is also located at the tumor cell membrane, although it does not hold a transmembrane domain." (PMID 26581653, 2015). "Our investigation for the first time demonstrates a link between loss of serglycin and reduced levels of VEGF in tumor tissue." (PMID 25978773, 2015). "Although serglycin is generally regarded as a committed intracellular proteoglycan, it has additionally been discovered to locate to the surface on different types of tumor cells, both in situ and in culture." (PMID 25978773, 2015). "Since there is currently no antibody available against serglycin that gives reproducible results in our model, we chose to address expression of serglycin by performing qPCR on material from whole tumor lysates of RTposSGwt and RTposSGko mice." (PMID 25978773, 2015). "This is the first study where the role of serglycin has been examined in an in vivo model of spontaneous tumor development." (PMID 25978773, 2015). "Our results show that serglycin influences tumor growth, angiogenesis, tumor vascular functionality and the availability of the pro-angiogenic modulators VEGF and HGF." (PMID 25978773, 2015). "Our data for the first time suggest that the presence of serglycin can suppress tumor expansion, and is of importance for the functionality of the tumor vasculature." (PMID 25978773, 2015). "Previous studies investigating the role of serglycin in tumor progression have focused on the expression of serglycin solely by the tumor cells." (PMID 25978773, 2015). "In the present study, we have addressed how serglycin affects spontaneous tumor progression in an immunocompetent mouse model." (PMID 25978773, 2015). "In this pilot study, serglycin was also found to be expressed in higher levels in stromal cells in tumor stroma as compared to normal tissue." (PMID 26581653, 2015). "Relative to whole tumor tissue, expression of serglycin by the tumor cells was 570x lower, which suggests that the major contribution of serglycin in the tumor tissue is likely to come from the stroma." (PMID 25978773, 2015). "Taken together, we conclude that serglycin affects multiple aspects of spontaneous tumor formation, which strengthens the theory that serglycin acts as an important mediator in the formation and progression of tumors." (PMID 25978773, 2015). "Serglycin was expressed by inflammatory and endothelial cells and fibroblasts in reactive tumor stroma especially at the invasive fronts suggesting a crucial role for serglycin in cancer spread." (PMID 26581653, 2015). "It has been shown that serglycin is highly expressed by tumor cells and promotes their aggressive phenotype and confers resistance against drugs and complement system attack." (PMID 24455486, 2014). "It is proposed that serglycin is bound on the surface of platelets, whereas serglycin has been identified on the surface of tumor cells." (PMID 24455486, 2014). "Serglycin seems to participate in tumor development in a manner that at least partially requires interactions between tumor cells and their microenvironment." (PMID 24455486, 2014).
tumor (continued). "Serglycin is among genes that over-expressed in six tumor cell lines of hematopoietic origin that resist in doxorubicin, methotrexate, cisplatin, and vincristine treatment compared to the drug sensitive parental cell lines." (PMID 24455486, 2014). "The tumor promoting properties of serglycin are dependent on the overexpression and secretion of glycanated serglycin." (PMID 24455486, 2014). "Rat L2 yolk sac tumor serglycin was the first PG gene to be cloned and remains until today the smallest known core protein (18 kDa)." (PMID 24455486, 2014). "SRGN expression in both hematopoietic cells and tumor tissues predicted poor patient outcomes." (PMID 41476965, 2025). "Serglycin knockdown decreased exosomal proteins and inhibited tumor-promoting actions, indicating that it may be a cancer target." (PMID 41188685, 2025). "Given that SRGN expression exhibits the highest positive correlation with macrophages among immune cells, this suggests that SRGN may enhance tumor immune evasion by modulating macrophage function via these checkpoints." (PMID 41476965, 2025). "The activation of hallmark pathways, including Hedgehog signaling, unfolded protein response, EMT, hypoxia, TGFβ signaling, cholesterol homeostasis, and the TNFA signaling pathway NFKB, mirrors the highly dynamic and adaptive of tumor cells with intensive SRGN expression in their tumorigenic niche." (PMID 40384866, 2025). "We hypothesize that the 24 h 3‐MA pretreatment may disrupt the positive feedback loop between CAFs and tumour cells by acutely interrupting SRGN secretion, leading to a sustained transition of CAFs to a low‐activity state." (PMID 41410182, 2025). "In WPOI 4–5 type OSCC, developing effective strategies to knock down SRGN may help overcome tumour progression induced by SRGN secretion." (PMID 41410182, 2025). "C2 SRGN+ subtype was significantly enriched in pathways related to leukocyte-mediated immune responses and the regulation of cell-cell adhesion, suggesting their potential role in the tumor immune microenvironment." (PMID 40688093, 2025). "Metascape enrichment analysis demonstrated significant enrichment of Hippo pathways and kinase activity in malignant cells with high SRGN expression, implying SRGN might affect tumor cell proliferation or apoptosis by regulating the Hippo signaling pathway." (PMID 40384866, 2025). "Mechanistically, SRGN activated YAP into the tumor cells' nucleus." (PMID 40384866, 2025). "SRGN is predominantly expressed in hematopoietic, endothelial, tumor, and embryonic stem cells." (PMID 40384866, 2025). "SRGN also directly stimulates oncogenic signaling in several tumor cell types." (PMID 36358747, 2022). "Overall, our results presented show that serglycin is one of many important molecules in the complicated network of factors determining the transition from the epithelial to the mesenchymal phenotype, and suggest that serglycin in tumor tissue is mainly produced by infiltrating immune cells." (PMID 35494005, 2022). "This may indicate that the increased expression of serglycin in the basal-like subtype is a consequence of immune infiltration in the tumor tissue." (PMID 35494005, 2022). "Weekly BLI analysis showed that SRGN knockdown markedly reduced GCTB tumor burden of mice." (PMID 34556636, 2021). "In addition, we also studied the different SRGN expression between tumor and adjacent normal tissues across all TCGA tumors." (PMID 32370744, 2020). "Moreover, we investigated the relationship between SRGN expression and the tumor-infiltrating immune cells in SKCM and SKCM-metastasis." (PMID 32370744, 2020). "Serglycin (SRGN) proteins are involved in tumor metastasis and may serve as a mediator of granule-mediated apoptosis." (PMID 31798630, 2019).
tumor (continued). "Our findings provide the first evidence of a critical role of serglycin in regulating the cargo and functions of tumor-derived exosomes and have a broad significance since a role for serglycin in different cancer progression (such as breast, lung, nasopharyngeal) is recently becoming apparent." (PMID 29088739, 2017). "In addition, our study demonstrates that SRGN does not affect cell growth in vitro, but decreases the ability of tumor formation in vivo, suggesting that tumor microenvironment has a great impact on SRGN tumorigenesis." (PMID 28692037, 2017). "This study found that glycoprotein SRGN is highly expressed in the TNBC tumor cells." (PMID 28692037, 2017). "Additionally, serglycin can also initiate an autocrine signaling pathway to enhance the proliferation and metastasing capacity of the tumor cells." (PMID 28445977, 2017). "The increased inflammatory cytokine levels found in the SG-/- tumour tissue may be due to a decreased serglycin-dependent proteolytical degradation of these cytokines, possibly owing to reduced mast cell protease activity." (PMID 27223472, 2016). "Therefore we assessed if the deletion of serglycin altered the level of inflammation in the primary tumours." (PMID 27223472, 2016). "Importantly, the expression level of serglycin in the SG-/- tumour tissue was 4.89 ±0.1 (log2), i. e. at background levels, whereas serglycin expression in the SG+/- tumour tissue was 10.52 ±0.4 (log2)." (PMID 27223472, 2016). "Although serglycin-deficient tumour cells were found in the circulation they failed to establish metastatic growth in lungs and liver at the experimental endpoint." (PMID 27223472, 2016). "Although we found tumour cells in the circulation, no tumour cells were detected in lungs of the serglycin-deficient PyMT+ mice, suggesting that extravasation is blocked." (PMID 27223472, 2016). "Furthermore, serglycin is expressed by platelets and it has been shown that platelets can bind to circulating tumour cells and thereby protect them from complement attacks." (PMID 27223472, 2016). "Immunohistochemistry (IHC) showed that S18 tumor tissues highly expressed serglycin in the stroma." (PMID 27809309, 2016). "IHC results also showed decreased serglycin expression in S18 SG KD2 tumor tissues." (PMID 27809309, 2016). "Interestingly, the stromal cells of the reactive tumor stroma were positive for serglycin, suggesting an enhanced biosynthesis for this proteoglycan in activated tumor microenvironment." (PMID 26581653, 2015). "Taken together, these studies point towards a mechanism whereby serglycin may modulate the tumor vasculature and thereby alter tumor cell behavior and tumor growth." (PMID 25978773, 2015). "To determine whether expression of serglycin was from tumor cells, we performed qPCR on cultured beta-TC-6 cells derived from a RIP-Tag mouse inulinoma." (PMID 25978773, 2015). "Recently, serglycin expression was related to cancer aggressivity both in tumor and stroma." (PMID 26694746, 2015). "Our data for the first time indicate that serglycin may act as a factor that can suppress spontaneous tumor expansion and highlight its involvement in tumor angiogenesis." (PMID 25978773, 2015). "The glycanation of serglycin may modulate the biological functions of tumor-derived serglycin since it seems to be important for serglycin's biological functions." (PMID 26581653, 2015). "The effect of serglycin expression on proliferation has been studied in tumor models." (PMID 26694746, 2015). "Notably, grade 2 and 3 neoplasms displayed very strong serglycin immunoreactivity, whereas the intensity of the two grade 1 malignancies was weak (+1) and moderate (+2)." (PMID 26581653, 2015). "Endothelial cells in tumor stroma had elevated serglycin cellular levels." (PMID 26581653, 2015). "Serglycin is constitutively secreted by lymphocytes and many hematopoietic tumor cell lines." (PMID 24455486, 2014).